CXCL10 (C-X-C motif chemokine ligand 10)
Diseases named in the same sentence as CXCL10 in open-access papers (continued):
Sharing a sentence is not in itself a finding about the gene and the disease.
tumor (continued). "However, in line with our observations, previous studies have also shown similar results in patients with other cancer types; high levels of CXCL10 were correlated with tumor recurrence or even a lower survival." (PMID 34944879, 2021). "These therapies or tumor-specific delivery of GM-CSF, CXCL10, and CCL2 could be successful with chemotherapy or in combination with checkpoint inhibitors." (PMID 34045467, 2021). "In addition, CD26/DPP4 cleaves ligands CXCL10 and CXCL12, which play a role in lymphocyte migration and tumor immune surveillance, thus increasing susceptibility to metastasis." (PMID 34055551, 2021). "The knockout of CXCL10 and depletion of Tregs inhibited tumor recurrence post reperfusion." (PMID 34360975, 2021). "Additionally, maintaining the biologically active form of CXCL10 enhanced the recruitment of lymphocytes to tumor sites and improved the treatment effect of immune checkpoint inhibitors." (PMID 34944392, 2021). "At this point, we do not exclude the possibility that following peripheral administration some of the injected CXCL10-Ig or CXCL9-Ig would enter the tumor site, and therefore may have an additional contribution to CXCR3+ cell recruitment to the TEM." (PMID 34944943, 2021). "In this study, we aimed to explore the role and mechanism of MDSC mobilization by CXCL10 signaling at early graft injury, which might lead to tumor recurrence post-liver transplantation." (PMID 33990548, 2021). "Activation of Wnt/β-catenin pathway in cancer cells inhibits secretion of CCL4 that is required for the recruitment of BATF-3 dependent dendritic cells to the tumor micro-environment, resulting in reduced levels of DC-derived CXCL10 and limited CD8+ CTL infiltration and cross-priming." (PMID 34774008, 2021). "Importantly, the clinical examination of CXCL10 in tumor tissues or serum is more feasible than applying the steps necessary for calculating the HRD score, and the prediction accuracy of upregulated CXCL10 is even better than the HRD score itself." (PMID 34158843, 2021). "While all three CXCR3 ligands were elevated in niches with actively growing tumor populations, IP-10 (CXCL10; growing 2.2-fold, emergent 1.5-fold) was present at markedly higher absolute levels than that of MIG (CXCL9; growing 1.5-fold, emergent 1.4-fold) and I-TAC (CXCL11; emergent 1.4-fold)." (PMID 34123844, 2021). "This pro-tumoral effect of CXCR3+ Tregs was also observed in HCC, where a correlation could be made between the infiltration of CXCR3+ Tregs in the TME induced by CXCL10 and increased tumor growth and HCC recurrence after liver transplantation." (PMID 33924428, 2021). "Thus, results for SOCS3 and ITGB5 verified an anti-inflammatory state; results for SOCS3 and AHSP verified a state of enhanced energy efficiency, and the result for CXCL10 (tumor suppressor) verified a higher defense response in the meditation group." (PMID 33804348, 2021). "Additionally, we inoculated CC cells overexpressing CXCL10 into nude mice subcutaneously and confirmed that CXCL10 promoted tumor growth in mice by observing tumor volume changes and detecting Ki-67 expression by immunohistochemistry." (PMID 34345201, 2021). "iNOS dependent anti-tumor TAMs skew the TME towards cytotoxicity through stimulating Th1 responses via secretion of CXCL9 and CXCL10, inducing cytotoxic CD8s through TNFα and IL1β, and direct killing of tumor cells through nitric oxide (NO) and Reactive Oxygen Species (ROS)." (PMID 34222022, 2021). "M1 tumor‐associated macrophages (TAMs) exert an antitumor function through the secretion of pro‐inflammatory cytokines such as IL‐12, tumor necrosis factor (TNF)‐α, CXCL‐10, and interferon (IFN)‐γ and by increasing the levels of nitric oxide synthase (NOS)." (PMID 33252831, 2021). "Along with this, early studies indicated that either overexpression of CXCL9 by cancer cell lines, or direct injection of CXCL10 to the tumor site, or targeted gene therapy of CXCL10, may limit cancer development." (PMID 34944943, 2021).
tumor (continued). "Our data thus demonstrate that treatment of some human GBM cells with GSK126 in vitro, results in a reversal of H3K27me3 that allows increased expression of CXCL9 and CXCL10 when induced by IFNγ leading to increased migration of T cells to tumor conditioned medium." (PMID 34336705, 2021). "cDC1s play a crucial role in the activation of anti-tumor immune responses, also acting locally in the TME, where, by producing the chemokines CXCL9 and CXCL10, they attract tumor-infiltrating T cells in the cDC1-rich areas and sustain local T cell restimulation." (PMID 34062821, 2021). "Additionally, CD4+ T cells secrete inhibitors of angiogenesis (e.g., CXCL9 and CXCL10) which can indirectly contribute to tumor dormancy by stabilizing the endothelium." (PMID 33738282, 2021). "Furthermore, CXCL10 has shown great anti-tumor potential; thus, we further showed that DPP4 was correlated with CXCL10, a novel anti-tumor chemokine, through physical interaction and co-expression by GENEMANIA analysis." (PMID 33614513, 2021). "The levels of molecules representing the function of M1 macrophages, such as CD86, MHC II, CXCL10, and IL-12, were markedly increased in the cryo-thermal therapy with sEV injection group compared to that from the tumor-bearing and cryo-thermal therapy-treated mice." (PMID 34681680, 2021). "CXCL10, upregulated in C2 (P < 0.001), is a pro-inflammatory cytokine involved in the chemotactic recruitment of macrophages, natural killer cells, dendritic cells, and active T lymphocytes to tumor cells." (PMID 33796460, 2021). "Several studies have demonstrated the significant role of CXCL10 in tumor, including PAAD." (PMID 33681290, 2021). "The expression of CXCL10 was higher in the tumor samples compared to the normal cases (p < 0.001)." (PMID 33681290, 2021). "The blocking of CXCL10 and IFNγ was able to slightly reduce the anti-tumor effect of CD20-TCB, suggesting that their inhibition might be able to at least partially block T cell recruitment to the tumor." (PMID 33406104, 2021). "Also, activation of β-catenin signaling decreased the infiltration of T cells to the tumor, whereas the chemokine CXCL10 had the opposite effect." (PMID 34462446, 2021). "First of all, when we used differently treated tumor cell culture media to process VE cells to detect angiogenesis, we found that overexpression of CXCL10 could inhibit angiogenesis, while the results of inhibiting CXCL10 are the opposite." (PMID 34794429, 2021). "In addition, increased expression of CD8α, CXCL9, CXCL10, Granzyme A (GZMA), Granzyme B (GZMB), and IFN-γ was observed in Six1-deficient tumor tissues." (PMID 34782761, 2021). "Thermal ablation upregulated Cxcl10, preferentially at distant tumor sites." (PMID 33441763, 2021). "In addition, referring to other studies, we found that CXCL10 has a different trend in other tumor studies." (PMID 34794429, 2021). "Using the same ovarian cancer model, Zou and colleagues showed that Ezh2 deficiency in T cells suppressed control of tumor progression, while combined Ezh2 and DNMT inhibitors improved the efficacy of anti-PD-1 therapy by increasing the production of CXCL9 and CXCL10." (PMID 33403469, 2021). "In the future, concomitant detections of interferon-γ and CXCL10 in tumor tissue sections and maybe in plasma samples might help to assess the immunosuppressive effects of gal-9 in various tumor contexts." (PMID 33664349, 2021). "Altogether, the dual effects of CXCL10 on the tumor and immune cells may occur simultaneously, and the overall outcome of the disease may be tumor-type dependent." (PMID 34944879, 2021).
tumor (continued). "Future studies will address whether CXCR3 expression on tumor cells results in a more tumorigenic TME in the context of CXCL9 or CXCL10 secretion." (PMID 34433873, 2021). "Interestingly, when the normal cases were added from the GTEx database, the expression of CXCL10 in the tumor cases was higher compared to the normal cases (p < 0.001)." (PMID 33681290, 2021). "Indeed, CXCR3 signaling through interaction with CXCL9 and CXCL10 has been shown to play a relevant role in tumor homing of effector T cells." (PMID 33746981, 2021). "In addition, they are associated with relatively lower level of tumor neoantigen load, TCR diversity, CXCL10, and the highest level of EDNRB, which are suggestive of an overall immunosuppressive TME with poor immunogenicity and T cell trafficking." (PMID 34208113, 2021). "In addition, tumor tissue analysis by histology revealed the same trend of increased CXCL10 expression in mice treated with CD20-TCB as compared to vehicle (increase of about 22 fold)." (PMID 33406104, 2021). "Furthermore, we discovered a positive relationship between the CXCL10 expression and tumor immune microenvironment (TIME), including infiltrating immune cells, neoantigen load and immune checkpoint blockade (ICB)." (PMID 34158843, 2021). "Inhibition of miR-21 in TAMs reduced tumor growth by inducing proinflammatory immune responses, including TNF, CXCL10, and CXCL9; this activates CD8+ T cells and causes the secretion of cytokines and chemokines, including IL-12 and CXCL10." (PMID 34827646, 2021). "For example, increased CXCL10 (IP10) following liver graft injury leads to ER stress-associated cisplatin-resistant HCC, and the neutralization of CXCL10 sensitizes cisplatin treatment, which suppresses tumor growth." (PMID 34671553, 2021). "However, CXCL10 can also mediate worse prognosis in some entities and chemotaxis of tumor-promoting cells, such as regulatory T cells (Tregs)." (PMID 34386037, 2021). "Additionally, the secretion of IFN-γ by Th1 cells can also promote CXCL9 and CXCL10 expression in the tumor microenvironment (TME) and therefore ensure the recruitment of CXCR3 expressing CD8+ T cells at tumor site." (PMID 34262562, 2021). "Similarly, in response to TLR4 stimulation by LPS, tumor-resident mast cells release CXCL10 and can recruit antigen specific T cells to B16-F10-OVA lesions." (PMID 33922465, 2021). "Added to this, there is the further complexity of tumours using epigenetic silencing to switch off production of Th1-based chemokines such as CXCL9 and CXCL10, a novel immune escape mechanism employed by tumours to reduce infiltration by cytotoxic effector cells." (PMID 34885108, 2021). "DPP4 can truncate CXCL10 to modify CXCL10–CXCR3 mediated influx of killer T cells in tumours." (PMID 34771657, 2021). "In particular, the interferon gamma-induced chemokine CXCL10, also known as IP-10, reported to sustain tumour growth via autocrine loops and to drive T lymphocytes and NK cells through activation of CXCR3, is often upregulated in the same manner or simultaneously with CC inflammatory chemokines." (PMID 33801414, 2021). "Additionally, two-way ANOVA demonstrates a significant effect of the tumor on the renal gene expression of Cxcl1, Cxcl9, and Cxcl10." (PMID 34445729, 2021). "Moreover, in a murine tumor model, anti-PD-1 therapy increases expression of CXCL10 at the tumor site." (PMID 33676416, 2021). "Compared to wild-type mice, knockout of CXCL10 or TLR4 significantly inhibited tumor development." (PMID 33990548, 2021). "After further analysis, C10-Tumor-INHBA and C04-Tumor-CXCL10 had enriched the highest level of cell death signaling, while the highest expression of CD274 (encoding PD-L1) was in C10 and C00, implying a limited correlation between tumor CD274 expression and tumor cell death." (PMID 33754038, 2021). "Previously shown in other tumors, CXCL10 can effectively inhibit tumor angiogenesis." (PMID 34794429, 2021).
tumor (continued). "Moreover, reduction of DPP4 activity using sitagliptin can protect the biological activity of CXCL10 to enhance T-cell recruitment into tumours and improve overall survival." (PMID 33513866, 2021). "Notably, among the four genes signature, only the CXCL10 gene was involved in tumor immunity; however, few studies have been conducted in oncology for the other three genes (TRPC7, CUX2, and COL2A1)." (PMID 34276760, 2021). "Our studies further certified that deficiency of CXCL10/TLR4 or TLR4 inhibitors could effectively reduce the monocytic MDSC recruitment with decreased MMP14, leading to the smaller tumor occupation." (PMID 33990548, 2021). "Depletion of CXCL9 and CXCL10 abrogated the anti-tumor activity of combined therapy." (PMID 33167311, 2020). "In addition, the IL-17R signaling in tumor cells blunts CXCL10 release thereby limiting CTLs influx in tumor bed." (PMID 33381121, 2020). "Furthermore, we analyzed the 50 highest TILRR-expressing and 50 lowest TILRR-expressing tumor tissue samples (TCGA database) to determine the relationship between the expression of CXCL10 and CXCL11 and the expression of TILRR in cancer tissues." (PMID 33031059, 2020). "In addition to being a potent chemoattractant for T lymphocytes, CXCL10 also inhibits tumor growth via suppressing angiogenesis." (PMID 32582551, 2020). "Extracellular S100A4 in the TME induces the release of pro-inflammatory factors (e.g., interleukin 6 (IL-6), interleukin 8 (IL-8), and C-X-C motif chemokine 10 (CXCL10)), which then converts monocytes into tumour-associated macrophages (TAMs), resulting in metastasis and drug resistance." (PMID 32722137, 2020). "A possible explanation behind the positive effect of eosinophils is their capacity to recruit cytotoxic T lymphocytes through CCL5, CXCL9, and CXCL10, to induce an anti-tumor phenotype in macrophages through TNFα and IFNγ and to normalize the tumor vasculature." (PMID 32793228, 2020). "Moreover, elevated CXCL10 in tumor cells can elicit potent tumor immunity, block cancer progression and enhance the clinical efficacy of immunotherapy." (PMID 32430013, 2020). "In part, the lack of toxicity may be due to CXCR3‐expressing CAR T cells being unable to efficiently home and infiltrate into the cerebellum, as the cerebellum expressed negligible levels of Cxcl9 and Cxcl10 when compared to the HER‐2‐E0771 tumours." (PMID 31803974, 2020). "CXCL10 is released upon tumor-toxic M1 macrophage polarization." (PMID 32316245, 2020). "For example, chemotactic cytokines, CXCL9 and CXCL10 may promote anti-tumor immune responses by recruiting NK and T cells into the tumor tissue thereby inhibiting angiogenesis." (PMID 32036449, 2020). "In addition, CXCL10 is important for recruitment of T lymphocytes such as CD8+ T cells in the tumor tissues, and is positively correlated with increased survival and favorable prognosis." (PMID 32483450, 2020). "Production of CXCL-10 (IP-10) is inversely correlated with tumor growth and angiogenesis." (PMID 32266155, 2020). "Chemokines CXCL9 and CXCL10 direct effector T cell trafficking and tumor infiltration." (PMID 32170083, 2020). "We identified that CXCL10 is a tumor-specific gene for DLBCL." (PMID 33240622, 2020). "In summary, CXCL10 is likely to restrict cancer development in many cancers by inducing anti-cancer immune response, and by a direct effect on epithelial cells within the tumor microenvironment and by direct suppression of tumor growth." (PMID 32547545, 2020). "Indeed, not only DC differentiated from bone marrow precursors in the presence of Tα1 expressed high levels of CXCL10 but CXCL10 was also expressed in the tumor microenvironment in response to Tα1." (PMID 32817121, 2020). "The increase in mRNA encoding expression of CXCR3, CXCL9 and CXCL10 (not CXCL11) as chemotactic chemokines suggests their involvement in the trafficking of anti‐tumor immune cells to the tumor site." (PMID 32821382, 2020).
tumor (continued). "In addition, intra-tumor induction of CXCL10 enhanced the infiltration of CXCR3+ cytotoxic T lymphocytes, thereby improving the antitumor effect of other therapies in some rodent solid tumor models." (PMID 32582551, 2020). "Engineering tumour cells with expression of CXCL10 can induce an anti‐tumour immune response." (PMID 32924269, 2020). "In addition, CXCL-10 was shown to increase tumour cell motility and fostered a more invasive phenotype, with establishment of prolific stress fibres inside tumour cells." (PMID 32806712, 2020). "Treatment with Romidepsin, a bicyclic class 1 selective HDAC inhibitor, has been shown to increase the expression of CCL5, CXCL9, and CXCL10 in tumor cells, promoting T cell recruitment into the tumor site and boost T cell-mediated anti-tumor function in multiple lung tumor models." (PMID 32560120, 2020). "Yet, it has been clearly shown that enhancement of CXCL10 in an in vivo set-up increases anti-tumor immunity and could be effectively used for cancer immunotherapy either as monotherapy, or in combined therapy with immune checkpoint inhibitors." (PMID 32547545, 2020). "High expression of CXCL10 in PAAD tumour indicated the poor survival of patients." (PMID 31913856, 2020). "Here, we found that circulating pDCs are severely impaired in IFN-α and CXCL10 production in MM patients, suggesting that tumor-mediated I-IFN inhibitory mechanisms might take place in the blood." (PMID 32731406, 2020). "It has been proven that CXCL10 could attenuate the process of new vessel formation and lead to reduced tumor growth in multiple human cancer models, such as non-small-cell lung cancer, colon–rectal cancer." (PMID 32089645, 2020). "Moreover, DNMT1 represses the tumor production of T helper 1 (TH1)-type chemokines CXCL9 and CXCL10 and the impacts on effector T-cell trafficking into the tumor microenvironment." (PMID 32708698, 2020). "IFN-γ and other cytokines, such as CCL2, CCL23, CXCL9, and CXCL10 have anti-tumor roles." (PMID 32346605, 2020). "Moreover, CCL2 and CXCL10 was present in the tumor and the tumor microenvironment and co-localized with almost all Nestin+, Iba-1+, CD163+ or CD16+ cells, suggesting the same distribution and localization." (PMID 32943658, 2020). "Based on these results of the analyses, it is inferred that CXCL10 might have a regulatory effect on tumor immunity." (PMID 33240622, 2020). "Moreover, CXCL1/GRO-α and CXCL10/IP-10 have been reported to support invasion, proliferation, and survival of tumor cells by acting on CXCR2 and CXCR3, respectively." (PMID 31256327, 2020). "In line with these evidences, the stimulation of mTOR cascade may enhance CXCL10-mediated T cells chemotaxis and anti-tumor immune responses in TME." (PMID 32483450, 2020). "Few roles have been ascribed to CXCL10 including chemo-attraction of NK cells, monocytes/macrophages, T cells and DCs, favouring adhesion of T cells to endothelial cells, anti-cancer/tumour action, and preventing angiogenesis and bone marrow colony development." (PMID 32045425, 2020). "Here, we show that suppression of the CCL2/CCR2 and CXCL10/CXCR3 axes by celecoxib in the tumor and the tumor microenvironment might contribute to antitumor effects." (PMID 32943658, 2020). "I-IFN exerts cancer cell intrinsic effects and modulates the immunoediting process, while CXCL10, also known as interferon gamma inducible protein 10 (IP-10), is a pro-inflammatory chemokine that is relevant for the recruitment of antigen-specific T cells into the tumor tissues." (PMID 32731406, 2020). "And our further analysis showed that CXCL10 might have a regulatory effect on tumor immunity, which is in accordance with characteristics of immune infiltration in DLBCL." (PMID 33240622, 2020). "CXCR3 is the receptor for CXCL10, a member of the CXC chemokine family with pro-inflammatory and anti-angiogenic properties that has been associated with a variety of human diseases, including tumor development, metastasis, and dissemination." (PMID 32256215, 2020).